TPO (thyroid peroxidase)
Diseases named in the same sentence as TPO in open-access papers (continued):
Sharing a sentence is not in itself a finding about the gene and the disease.
psoriatic arthritis (3 papers, 2019 to 2024). Joint inflammation associated with psoriasis. "From five patients with nail psoriasis and from whom four (80%) had associated psoriatic arthritis, TPO Ab and Tg Ab positive in three (60%) and two (40%), respectively." (PMID 31157131, 2019). "From eight psoriatic arthritis patients, four (50%) had positive TPO Ab and three (37.5%) had Tg Ab positive." (PMID 31157131, 2019). "A significant increase in the incidence of subclinical hypothyroidism, TPO and Tg Abs positive, and hypo-echogenicity on thyroid ultrasound was present in patients with psoriatic arthritis, especially among women." (PMID 31157131, 2019).
psychosis (3 papers, 2021 to 2024). "Studies have shown that patients with normal thyroid hormone levels but elevated anti-TPO antibodies can be at risk of developing neuropsychiatric symptoms such as psychosis." (PMID 39539911, 2024). "In this patient, her elevated anti-TPO antibodies indicated ongoing autoimmune activity, suggesting that her psychosis could be linked to subtle neuroinflammation rather than severe thyroid hormone dysfunction." (PMID 39539911, 2024). "The patient’s elevated anti-TPO antibodies, despite normal TSH, T3, and T4 levels, suggest that autoimmune activity likely triggered neuroinflammation, leading to psychosis." (PMID 39539911, 2024).
pulmonary embolism (3 papers, 2019 to 2025). The obstruction of the pulmonary artery or one of its branches by an embolus, sometimes associated with infarction of the lung. "Following a failure to improve after splenectomy, the patient resumed TPO therapy with a significant rise in his platelet count and then suffered a lethal pulmonary embolism." (PMID 38999278, 2024).
sarcoidosis (3 papers, 2021 to 2022). Sarcoidosis is a multisystemic disorder of unknown cause characterized by the formation of immune granulomas in involved organs. "Using an regression algorithm, we identified a panel of 11 IgM autoantiboides including BPI, Fibrinogen IV, Hemocyanin, Histone H2B, Histone H3, Matrigel, Prothrombin protein, Sm, SmD, TPO and Vimentin, which can efficiently distinguish between sarcoidosis and healthy controls." (PMID 36264970, 2022). "Sarcoidosis patients have also been shown to have higher levels of thyroglobulin antibodies and/or thyroid peroxidase antibodies compared to control subjects, although the pathogenetic role of these antibodies in the association between sarcoidosis and autoimmune thyroid disease is unknown." (PMID 35441568, 2022).
syphilis (3 papers, 2015 to 2024). A contagious bacterial infection caused by the spirochete Treponema pallidum. "Serum studies demonstrated normal antinuclear antibodies (ANA), thiamine, anti-Ro, anti-La, thyroid stimulating hormone (TSH), free T3/free T4 (fT3/T4), thyroid peroxidase (TPO) and thyroglobulin (TG) antibodies, syphilis screen, borrelia IgG/IgM antibodies, C-reactive protein (CRP)." (PMID 39628892, 2024).
thyroid abnormalities (3 papers, 2023 to 2025). "Our findings of a normal thyroid US in 91% of the investigated children is in agreement with the observations above, considering also that the two patients that presented mild thyroid abnormalities at US had a transient TSH elevation and anti-TPO antibody positivity, and none required therapy." (PMID 40128881, 2025).
vasculitis (3 papers, 2019 to 2024). "Finally, vasculitis resulting in abnormalities in cortical perfusion might be another possible mechanism, since abnormalities in cortical perfusion were frequently found in a serial of BD patients with TPO-ab positivity." (PMID 31791284, 2019).
acute myeloid leukemia (2 papers, 2021 to 2022). Acute myeloid leukemia (AML) is a group of neoplasms arising from precursor cells committed to the myeloid cell-line differentiation. "TPO and c-Mpl, as evaluated in the present study, have been found to be associated with platelet production and may affect the chemotherapy efficacy of acute myeloid leukemia (AML)." (PMID 33959189, 2021).
adenoma (2 papers, 2008 to 2015). A neoplasm arising from the epithelium. "TPO expression was moderate to high in all adenomas (mean 4.5), regularly distributed in the cytoplasm with a marked apical predominance." (PMID 26300979, 2015). "Microfollicular adenomas and MIFCs show increased TPO levels, which may reflect a failure of these invasive cells to lose function and differentiation despite their neoplastic course." (PMID 26300979, 2015).
AIDS (2 papers, 2023 to 2024). A syndrome resulting from the acquired deficiency of cellular immunity caused by the human immunodeficiency virus (HIV). "Patients with exclusively AITDs and other AIDs regardless of the presence of AITDs had higher frequency of anti-TPO above 35UI/ml, than patients without any AIDs, [(173 (65.3) vs 18 (32.7) vs 227 (16.8), respectively, < 0.001]." (PMID 38297335, 2024). "Two children not diagnosed with AIDs had autoimmune markers—one had positive anti-nuclear antibodies, and the other had positive perinuclear ANCA and anti-TPO Antibodies." (PMID 38068533, 2023).
anaplastic cancer (2 papers, 2010 to 2018). "As expected human anaplastic cancer cells (SW1736 and C643) poorly expressed TPO on their cell surface." (PMID 20145622, 2010).
autoimmune polyglandular syndrome (2 papers, 2021 to 2025). "Thyroid function tests indicated subclinical hypothyroidism with negative anti-thyroid peroxidase (anti-TPO) antibodies, excluding autoimmune polyglandular syndrome." (PMID 41399549, 2025).
Central hypothyroidism (2 papers, 2024 to 2025). A type of hypothyroidism due to an insufficient stimulation of an otherwise normal thyroid gland. "Four women (3.1%, n = 131) were suspected having central hypothyroidism as they did not have s-anti-TPO and their s-TSH were low to normal with low fT4 levels." (PMID 38078923, 2024).
chronic superficial gastritis (2 papers, 2021 to 2024). "Diagnostic results indicated positive intrinsic factor antibodies, a gastric biopsy compatible with gastritis, elevated thyroid peroxidase antibodies, and significant findings from a thyroid ultrasound." (PMID 39816290, 2024).
colon carcinoma (2 papers, 2019 to 2022).
Down syndrome (2 papers, 2023 to 2025). "Also, antibodies against thyroid peroxidase (TPO) are found in up to 31% of patients with Down syndrome." (PMID 38066740, 2023).
fibromyalgia (2 papers, 2022 to 2024). A chronic disorder of unknown etiology characterized by pain, stiffness, and tenderness in the muscles of neck, shoulders, back, hips, arms, and legs. "Additionally, TPO-Ab-positive RA patients are more likely to develop symptoms such as fibromyalgia or chronic generalized pain." (PMID 39314521, 2024).
glioma (2 papers, 2013 to 2019). A benign or malignant brain and spinal cord tumor that arises from glial cells (astrocytes, oligodendrocytes, ependymal cells). "The following four probes cg19681793 (targeting THBS2), cg24215279 (targeting TPO), cg11235583 (targeting CLCNKB), and cg14158583 (targeting PVRL4) have also been confirmed to target effective genes with different methylation status in different IDH-dependent glioma subtypes." (PMID 31803734, 2019).
Hepatitis (2 papers, 2018 to 2023). Inflammation of the liver. "Lactate dehydrogenase test, Polymerase chain reaction (PCR) and ferritin were on high levels, serum iron was on low levels, negative serology for HIV, Hepatitis B and Hepatitis C, anti-thyroid peroxidase antibodies (anti-TPO antibodies) and the thyroid hormones within normal limits." (PMID 29796437, 2018).
Hyperinsulinemia (2 papers, 2014 to 2026). An increased concentration of insulin in the blood. "The prevalence of hyperinsulinemia was significantly higher in Hashimoto patients with higher levels of Anti TPO antibodies more than 1000 IU/ml." (PMID 25364704, 2014).
hyperphosphatemia (2 papers, 2011 to 2022). Abnormally high level of phosphate in the blood. "Hypocalcemia (0.75 mmol/L), hyperphosphatemia (110 mmol/L), and elevated levels of thyroid stimulating hormone, thyroid peroxidase antibody, and anti-TG were detected." (PMID 36276061, 2022).
hyperthyroxinemia (2 papers, 2021 to 2022). Abnormally elevated thyroxine level in the blood. "Both TPO Ab-positive and TPO Ab-negative groups had comparable disease activity (hyperthyroxinemia, TSH-R Ab titer, uptake at scintigraphy)." (PMID 35687484, 2022).
Hypokalemia (2 papers, 2020 to 2021). An abnormally decreased potassium concentration in the blood. "The older sister of proband B had chronic hypokalemia, accompanied by thyroid dysfunction and elevated thyroid peroxidase antibodies and TG antibodies." (PMID 34046503, 2021).
hypophysitis (2 papers, 2015 to 2024). Inflammation of the pituitary gland. "Furthermore, the risk of developing non-thyroid endocrine irAEs such as hypophysitis, may be increased in patients who are positive for anti-thyroid peroxidase antibodies at baseline." (PMID 38681767, 2024). "On diagnosis of hypophysitis and later on SREAT both TSH and thyroid hormone levels were expectably low, and anti-TPO and anti-TG antibodies were elevated." (PMID 26209970, 2015).
liver cirrhosis (2 papers, 2023 to 2024). "Additionally, patients with liver cirrhosis are often associated with a potentially increased risk of vein thrombosis, and the use of TPO-RAs may further increase the risk of thrombosis." (PMID 36258065, 2023).
migraine (2 papers, 2015 to 2017). "TSH, fT4, TPO-ab and TG-ab concentrations were not significantly different between SCH patients with migraine and without migraine." (PMID 28132307, 2015).
myelitis (2 papers, 2014 to 2016). An inflammatory process affecting the spinal cord. "An AQP4 antibody negative female patient had very high titers of TG-Ab and TPO-Ab, and these fluctuating levels were associated with myelitis relapse." (PMID 25093326, 2014). "In 96 patients (NMO, n = 19; TM, n = 25; MS, n = 52) without treatment, serum levels of TSH, TG-Ab and TPO-Ab were significantly different between patients with and without myelitis (p<0.01)." (PMID 25093326, 2014). "Abnormalities of FT3, TSH, TG-Ab, TPO-Ab, gender, and age in patients with myelitis were significantly different to patients without myelitis." (PMID 25093326, 2014). "Furthermore, levels of TSH, TG-Ab, TPO-Ab in patients with myelitis were significantly different to patients without myelitis." (PMID 25093326, 2014).
myxedema (2 papers, 2015 to 2023). A condition characterized by severe hypothyroidism that is caused by autoimmune thyroid gland disorders, surgical reduction of thyroid tissue, radiation exposure, and viral infections. "TPO is critical to the production of thyroid hormones that can impact immune function and is also associated with mucinosis (myxedema), a disease characterized by increased glycosaminoglycan deposition in the skin." (PMID 26569114, 2015).
nasopharyngeal carcinoma (2 papers, 2020 to 2021). A carcinoma arising from the nasopharyngeal epithelium. "After radiotherapy, thyroid inflammation occurs in patients with nasopharyngeal carcinoma, which results in increased TG-Ab and TPO-Ab expression." (PMID 32461982, 2020).
otitis media (2 papers, 2024). Inflammation of the anatomical structures of the middle ear, which is most often caused by an infectious process. "Elevated levels of anti-TPO in individuals with history of use of ear tubes suggests an interplay between otitis media and endocrine dysfunction in DS63." (PMID 38946973, 2024).
otitis media with effusion (2 papers, 2024). Otitis media associated with accumulation of fluid in the middle ear. "However, unexpectedly, TPO+ status also associates with higher rates of use of pressure equalizing (PE) tubes employed to alleviate the symptoms of recurrent ear infections and otitis media with effusion (OME), which is common in DS38." (PMID 38946973, 2024).
pneumonia (2 papers, 2022 to 2024). An acute, acute and chronic, or chronic inflammation focally or diffusely affecting the lung parenchyma, caused by an infection in one or both of the lungs (by bacteria, viruses, fungi, or mycoplasma.). "Large TFT (TSH, T3, T4, anti-TPO) and laboratory data of 201 patients with mild, moderate or severe pneumonia on CT were scanned retrospectively." (PMID 36381073, 2022). "In our study, large TFT (TSH, T3, T4, anti-TPO) and laboratory data of 201 patients with mild, moderate or severe pneumonia on CT who were PCR+ were scanned retrospectively." (PMID 36381073, 2022).
renal cell carcinoma (2 papers, 2022 to 2025). "RCC: renal cell carcinoma; a-TPO: anti-thyroid peroxidase antibody; ATG: anti-thyroglobulin." (PMID 41487768, 2025).
renal dysfunction (2 papers, 2021 to 2025). "Elevated anti-TPO levels are associated with renal dysfunction in elderly hypothyroid patients, suggesting a potential role for anti-TPO in renal impairment." (PMID 40937419, 2025). "There was a significant decrease in eGFR this time in anti TPO positive patients along with increased serum creatinine, uric acid, and urine microalbumin levels suggesting a strong association between increased anti TPO levels and renal dysfunction among hypothyroid patients." (PMID 40937419, 2025). "The proportion of patients with hepatic dysfunction, renal dysfunction, high triglyceride and total cholesterol levels, and positive thyroid peroxidase or thyroglobulin antibodies was similar between the two groups." (PMID 34512539, 2021).
rheumatic disease (2 papers, 2017 to 2021). "The joint pains were evaluated by European Union League against rheumatism (EULAR-CSA) score and compared with serum DHEAS, RA factor, Anti-TPO antibody, highly sensitive C-recative protein (hsCRP), vitamin D levels." (PMID 33592022, 2021).
selenium deficiency (2 papers, 2024 to 2025). A nutritional deficiency disease resulting from inadequate selenium levels in the body, which can lead to impaired function of selenoproteins essential for antioxidant defense and thyroid hormone metabolism. "Moreover, clinical research suggests that selenium deficiency is linked with a higher risk of elevated anti-thyroid antibody levels, while selenium supplementation has been shown to reduce thyroid peroxidase antibody levels." (PMID 40457391, 2025).
Splenomegaly (2 papers, 2025). Abnormal increased size of the spleen. "F4/80+ macrophages are increased in TPO‐RA mice, suggesting that splenomegaly is associated with their buildup in the spleen." (PMID 40690545, 2025). "As we observed a significant improvement in BM fibrosis, splenomegaly, and monocytosis in the TPO‐induced PMF model, a robust model for MPN associated with fibrosis, we next sought to validate these findings in a JAK2V617F‐induced murine model of MPN/PMF as a highly patient‐relevant model." (PMID 40823315, 2025). "To understand the molecular basis of EMH, we exploited a MF mouse model obtained through the administration of a TPO‐RA, Romiplostim (Nplate), which develops a sizable splenomegaly in 14 days." (PMID 40690545, 2025).
steatosis (2 papers, 2020 to 2024). Increased lipid within the cytoplasm of cells. "Circulating anti-TPO was an independent factor associated with advanced steatosis (odds ratio 9.5, 95% confidence interval 1.3–68.3)." (PMID 39420912, 2024). "When anti-TPO positivity was added to the model (Step 2), a trend toward an association with severe steatosis was observed." (PMID 39420912, 2024).
systemic sclerosis (2 papers, 2024 to 2025). A chronic disorder, possibly autoimmune, marked by excessive production of collagen which results in hardening and thickening of body tissues. "Other studies revealed that both anti-TPO and anti-Tg antibodies are found with a higher prevalence in systemic sclerosis patients." (PMID 38256549, 2024).
Thyroid storm (2 papers, 2022 to 2023). "Eight days later, he presented with signs of thyroid storms, such as tachycardia, hyperthermia, sweating and irritation, and his thyroid function tests revealed high levels of TPO-Ab, TR-Ab, TG-Ab, FT3 and FT4." (PMID 35794521, 2022).
abortion (1 paper, 2022). the ending of pregnancy by removing a fetus or embryo before it can survive outside the uterus. "Thyroid peroxidase antibodies (TPO-Ab) may be associated with pregnancy outcomes in unexplained recurrent spontaneous abortion with normal thyroid function." (PMID 36120428, 2022). "This study aimed to investigate the relationship between TPO-Ab and the first trimester miscarriage rate/live birth rate in women of unexplained recurrent spontaneous abortion with normal thyroid function." (PMID 36120428, 2022).
acne (1 paper, 2021). An inflammatory process of the sebaceous glands which is characterized by comedones, nodules, papules and/or pustules on the skin. "The risk analysis indicated that raised values of anti-TPO (2.91 times greater) correlated with high anti-thyroglobulin (TG) values (4.36 times greater) doubled the risk of developing severe acne in patients." (PMID 33924808, 2021). "The data analysis showed that the presence of increased anti-TPO (2.91 times) and the association with anti-TG (4.36 times) doubled the risk of developing severe acne in patients with AIT." (PMID 33924808, 2021). "The risk analysis indicated that the presence of increased anti-TPO (2.91 times) and the association with anti-TG (4.36 times) doubles the risk of developing severe acne in patients with AIT." (PMID 33924808, 2021). "The analysis of the anti-TPO values according to the degree of acne revealed significantly higher values (F = 5.126, p = 0.007) in patients with severe acne compared with those with moderate acne." (PMID 33924808, 2021). "In 2017, Stewart and Bazergy determined a 24.5% prevalence of anti-TG antibodies, and 18% of the anti-TPO antibodies were found in adult women with acne, thus noting significantly higher values compared with the control group." (PMID 33924808, 2021). "The results of the present study indicate increased incidence of AIT in the studied population with acne; 59.3% patients had high serum levels of anti-TG antibodies and 62.2% of anti-TPO antibodies." (PMID 33924808, 2021). "The TSH and anti thyroidperoxidase (TPO) values did not influence the severity of the acne (p = 0.494; p = 0.111), while the anti-TG values were associated with severe acne (p = 0.007)." (PMID 33924808, 2021). "Anti-TG values did not significantly influence the severity of acne, while anti-TPO values were significantly higher in patients with severe acne." (PMID 33924808, 2021).
Acute encephalopathy (1 paper, 2023). "In duration of follow up from 6 months up to 5 years there are 204 patients who presented at our center with unexplained acute encephalopathy, 31 (15%) tested positive for the anti-TPO or anti-Tg antibody." (PMID 37737161, 2023).
alcohol- (1 paper, 2020). "ACT and Sil failed to affect the hepatic levels of TPO, RBP4, IL-23, ICAM-1, NGAL, and VCAM-1 in acute alcohol-injured mice compared with the model group." (PMID 32719658, 2020).
Alopecia universalis (1 paper, 2026). Alopecia universalis is the most severe form of alopecia areata, an inflammatory disease of the hair follicle, which is characterized by a complete loss of hair of the scalp and all the hair-bearing areas of the body. "We report a case of a 44-year-old woman with both alopecia universalis and HT who experienced normalization of TPO antibody levels, no longer requiring thyroid hormone treatment following JAK inhibitor therapy for alopecia universalis-suggesting possible reversal of HT." (PMID 42039112, 2026).